TREM2 (triggering receptor expressed on myeloid cells 2)
Diseases named in the same sentence as TREM2 in open-access papers (continued):
Sharing a sentence is not in itself a finding about the gene and the disease.
epilepsy (7 papers, 2020 to 2026). A brain disorder characterized by episodes of abnormally increased neuronal discharge resulting in transient episodes of sensory or motor neurological dysfunction, or psychic dysfunction. "Using GEO database, we found that DPP4 and Cp overexpression was associated with the dysregulation of TREM2 and epilepsy." (PMID 33975617, 2021). "Triggering receptor expressed on myeloid cell 2 (TREM2)-mediated microglial phagocytosis of inhibitory synapses may play a pivotal role in epileptogenesis; however, the role of TREM2 in FS-induced epilepsy remains unclear." (PMID 41965330, 2026). "Administration of a CD33 agonist (monosialoganglioside 1, GM1), a negative moderator of TREM2 that reduces its levels, attenuated microglial phagocytosis of inhibitory synapses and weakened susceptibility to epilepsy and seizures." (PMID 41965330, 2026). "The triggering receptor expressed on the myeloid cells 2 (TREM2) gene may also connect AD and epilepsy." (PMID 38999445, 2024). "Therefore, we studied the regulation of TREM2 expression in epilepsy via the PI3K/Akt pathway in an epileptic rat model." (PMID 35432728, 2022). "Increasing evidences showed that TREM2 exhibited some protective effects, including anti-inflammation, autophagy inhibition and enhanced phagocytosis in neurodegenerative diseases, such as AD, Parkinson's disease (PD), and epilepsy." (PMID 33065553, 2020). "The R47H variant of the TREM2 gene, associated with a 2–4-fold increased risk of AD, has been found to elevate epileptic activity in mouse models Genetic studies have identified multiple genes, including APOE, that are implicated in common pathogenetic mechanisms between AD and epilepsy." (PMID 38999445, 2024). "The expression of TREM2, PI3K, P-Akt, and GSK3β was significantly lower in the epilepsy group rats than in the CON and sham group rats, and there was no significant change in Akt expression." (PMID 35432728, 2022). "In epilepsy, high levels of C1q, C3, and TREM2/DAP12 receptor have been found in hippocampal samples from different forms of human and animal models of epilepsy, suggesting an abnormal phagocytosis of synapses and/or neurons." (PMID 32521797, 2020). "The current study defined the potential role of ABP in inhibiting the development of epilepsy, indicating that ABP could upregulate TREM2 to alleviate neuronal apoptosis, by activating the PI3K/Akt/GSK-3β pathway and oxidative stress in epilepsy." (PMID 35432728, 2022). "Trem2 also could inhibit neuronal apoptosis and hippocampal oxidative stress via increased SOD and GPx and reduce levels of MDA through activation of the PI3K/Akt pathway in an epilepsy rat model." (PMID 37605727, 2023).
fibrosis (7 papers, 2020 to 2025). the formation of excess fibrous connective tissue in an organ or tissue in a reparative or reactive process. "The role of TREM2 in the resorption of the fibrotic scars was also evaluated in a CCl4-induced fibrosis model." (PMID 39172787, 2024).
inflammatory bowel disease (7 papers, 2018 to 2025). A spectrum of small and large bowel inflammatory diseases of unknown etiology. "However, Danese’s group reported that TREM-2 deficient DCs produced lower levels of inflammatory cytokines in a murine model of inflammatory bowel disease." (PMID 29887864, 2018). "In a mouse model of inflammatory bowel disease, TREM2 expression on intestinal lamina propria-dendritic cells promoted downstream TLR signaling." (PMID 38236825, 2024). "TREM2 knockout mice produced lower inflammatory cytokine levels and reduced bacterial killing and T-cell activation than cells from wild-type mice in the inflammatory bowel disease model." (PMID 34356130, 2021). "However, increased TREM2 expression in myeloid cells can increase phagocytic ability and is elevated in patients with inflammatory bowel disease." (PMID 39867899, 2024). "TREM‐2 has been also suggested to evoke the inflammatory responses in inflammatory bowel disease (IBD) by affecting the function of dendritic cells." (PMID 39898124, 2025).
Anxiety (6 papers, 2018 to 2025). Intense feelings of nervousness, tension, or panic often arise in response to interpersonal stresses. "Mice with T2DM combined with OSA exacerbated anxiety via the downregulation of TREM2, causing heightened IFNAR1-STAT1 pathway activation and consequently increasing proinflammatory microglia." (PMID 38956653, 2024). "Conversely, mice with T2DM combined with OSA may exacerbate anxiety via the downregulation of TREM2, causing heightened IFNAR1-STAT1 pathway activation and consequently increasing proinflammatory microglia." (PMID 38956653, 2024). "Based on this notion, the increased exacerbation of anxiety in T2DM mice with comorbid OSA may be due to the decrease in TREM2, which induces a further increase in proinflammatory microglia and additional neurological destruction." (PMID 38956653, 2024). "In the OFT and EPM, we found that TREM2 upregulation could alleviate anxiety‐like behaviours in WT TBI mice, as evidenced by more exploring time in the centre zone and open arms, respectively (p < 0.05)." (PMID 38649789, 2024).
Atrophy (6 papers, 2013 to 2026). Any weakening or degeneration, especially through lack of use. "We suggest that a family history of consanguinity along with somewhat atypical features, such as seizures and callosal atrophy, in a patient presenting with a bvFTD phenotype should prompt the diagnostician to look for a likely TREM2 homozygous or compound heterozygous mutation." (PMID 23870839, 2013). "Trem2 knockout mice had reduced macrophage infiltration at 3 dpi, and reduced hippocampal atrophy, and improved behavioral outcome at 120 dpi in a lateral fluid percussion model, suggesting a role for TREM2 in outcome after cerebral contusion." (PMID 31440141, 2019).
brain tumors (6 papers, 2020 to 2026). "In both human- and mouse brain tumors, Siglec-10+ cells co-express the microglia-associated molecule TREM2." (PMID 41606146, 2026). "Moreover, it was discovered that excessive TREM2 expression in malignant brain tumors is linked to a worse prognosis, while low TREM2 expression is linked to a higher chance of survival." (PMID 39015316, 2024). "In addition, previous studies showed that TREM2 (Triggering Receptor Expressed On Myeloid Cells 2) acts as a risk factor for both AD and brain tumors." (PMID 37542274, 2023). "Moreover they noticed that malignant brain tumors and AD have been shown to exhibit overexpression of the same genes, for example, TREM2 (triggering receptor expressed on myeloid cells 2)." (PMID 34523079, 2021). "We suppose that TREM-2+ monocytes arise as a contraregulatory subpopulation of cells with the effort to downregulate the exaggerated inflammation—both systemic and local—and potentiate the phagocytosis in the brain tumor." (PMID 32684831, 2020). "Moreover, it is also worthwhile to investigate the therapeutic potential of TREM2 blockade in metastatic brain cancers or primary brain tumors, as these tumors might contain abundant TREM2-expressing microglia and monocyte-derived TAMs." (PMID 33037186, 2020).
cerebral amyloid angiopathy (6 papers, 2020 to 2025). "In Tg-SwDI mice susceptible to cerebral amyloid angiopathy, TREM2 KO led to significantly reduced severity of cerebral amyloid angiopathy compared to wild type, despite increased overall amyloid deposition." (PMID 41168805, 2025). "ApoE4 Female: ↑ microbleeds, cerebral amyloid angiopathy, soluble Aβ, ↓ microglial plaque coverage, ↓ TREM2 expression, and ↑ amyloid levels." (PMID 39126053, 2024).
coronary artery disease (6 papers, 2023 to 2025). "A study comparing serum TREM2 levels in coronary artery disease patients with healthy controls suggests that higher soluble TREM2 levels can be used as a biomarker for plaque rupture and predictor of cardiovascular death." (PMID 36994095, 2023).
non-small cell lung carcinoma (6 papers, 2021 to 2025). A group of at least three distinct histological types of lung cancer, including non-small cell squamous cell carcinoma, adenocarcinoma, and large cell carcinoma. "Preclinical studies across various cancer types suggest that TREM2 is a promising therapeutic target for cancer immunotherapy.In non-small cell lung cancer (NSCLC), TREM2+ TAMs are enriched in immunologically “cold” tumors and correlate with poor response to anti–PD-1 therapy." (PMID 40821795, 2025).
Onset (6 papers, 2013 to 2024). The age group in which disease manifestations appear. "Genetic risks for sporadic, late-onset AD have been linked to Triggering Receptor Expressed on Myeloid Cells 2 (TREM2), which is expressed in microglia." (PMID 36331399, 2022). "One such example is provided by the triggering receptor expressed on myeloid cells 2 (TREM2) whose mutations have been identified as major risk factors for late-onset AD." (PMID 34893068, 2021). "Rare variants of TREM2 have augmented risk of developing late-onset AD." (PMID 38836051, 2024). "Through genome-wide association studies and other methods, it has been found that many genes related to lipid metabolism, immune response, and endocytosis are correlated with the occurrence of late-onset AD, including APOE, TREM2, PICALM, and CLU." (PMID 33806413, 2021).
prostate tumor (6 papers, 2024 to 2026). "Prostate tumor-derived apoE induces senescence of Triggering Receptor Expressed on Myeloid cells 2 (TREM2)-positive neutrophils." (PMID 41465180, 2025). "For example, APOE secreted by prostate tumor cells can bind to neutrophils via TREM2, inducing cell senescence." (PMID 40678806, 2025). "Recent studies have indicated that APOE secreted by prostate tumor cells binds to triggering receptor expressed on myeloid cells 2 (TREM2) on neutrophils, thereby promoting their senescence." (PMID 39524226, 2024). "By combining single-cell and spatial transcriptomics, along with flow cytometry and immunohistochemical analyses, we now reveal that prostatic tumors of such mice are hypoxic and progress within a complex immune microenvironment, including neutrophils, TREM2+ macrophages, and CCR2+ myeloid cells." (PMID 41896221, 2026). "For instance, prostate tumor cells secrete APOE, which binds to TREM2 on neutrophils to promote their senescence." (PMID 39990672, 2025).
triple-negative breast carcinoma (6 papers, 2021 to 2026). An invasive breast carcinoma which is negative for expression of estrogen receptor (ER), progesterone receptor (PR), and human epidermal growth factor receptor 2 (HER2). "Triple-negative breast cancer (TNBC) bone metastasis is characterized by an immunosuppressive microenvironment dominated by triggering receptor expressed on myeloid cells 2 (TREM2) + myeloid cells, which promote osteoclastogenesis, as well as T cell exclusion." (PMID 41945876, 2026). "In triple-negative breast cancer (TNBC), high TREM2 expression has been closely associated with shortened overall OS and RFS." (PMID 40242752, 2025). "Conversely, TREM2+ macrophages likely determined an immunosuppressive metastatic niche, with TREM2 predicting poorer overall survival and relapse-free survival in triple-negative breast cancer." (PMID 39184073, 2024).
autism (5 papers, 2014 to 2025). Persistent deficits in social interaction and communication and interaction as well as a markedly restricted repertoire of activity and interest as well as repetitive patterns of behavior. "RA supplementation effectively rescued these TREM2 deficiency‐induced abnormalities by normalizing microglial activity and synaptic pruning deficits and significantly ameliorating autism‐like behavioral phenotypes." (PMID 41476737, 2025). "RA supplementation reversed many of the pathological alterations associated with TREM2 reduction and improved autism‐like behaviors in the affected rats." (PMID 41476737, 2025). "This indicated that RA modulated TREM2‐dependent mechanisms in autism pathogenesis and ameliorated autism‐like behaviors associated with TREM2 deficiency." (PMID 41476737, 2025). "Some important microglia genes, such as TREM2 (as the microglia innate immune receptor gene involved in synapse pruning) are also linked to autism pathogenesis." (PMID 37107654, 2023). "Our previous studies demonstrated that prenatal VPA exposure induced autism‐like behaviors in offspring by suppressing RA/RARα signaling, downregulating TREM2 expression, and activating microglia." (PMID 41476737, 2025). "The RA/RARα‐TREM2 axis represents a crucial molecular node governing microglial function and autism‐like neurodevelopmental abnormalities." (PMID 41476737, 2025). "Downregulation of TREM2 induces autism‐like behaviors in healthy rats by impairing microglial function and triggering aberrant synaptic pruning." (PMID 41476737, 2025). "In our study using TREM2‐kd rats, decreased brain TREM2 expression coincided with reduced serum sTREM2 levels and the emergence of autism‐like behaviors." (PMID 41476737, 2025). "In contrast, RA supplementation increased brain TREM2 expression, elevated serum sTREM2 levels and ameliorated autism‐like behaviors." (PMID 41476737, 2025). "Concurrently, we discovered that retinoic acid receptor α (RARα) can bound to the promoter region of the TREM2 gene, regulating its transcription and ameliorating autism‐like behaviors in valproic acid (VPA) model rats." (PMID 41476737, 2025). "Considering these data, further study of the epigenetic dysregulation of TREM2 is warranted in autism." (PMID 37107654, 2023). "In mice, the lack of expression of TREM2 is associated with autism-like behavior and, in humans, a reduced TREM2 protein level correlates with the severity of autism symptoms." (PMID 37107654, 2023). "The expression of TREM2 was highest of all microglial markers, approximately 1.75-fold higher in autism brain tissue than controls (P = 0.0016)." (PMID 24410870, 2014). "The results demonstrated that TREM2 reduction elicited the expected pathological outcomes, including aberrant microglial activation and polarization, impaired synaptic pruning, and manifestation of autism‐like behaviors." (PMID 41476737, 2025). "In contrast, the expression of microglial markers TREM2, DAP12, CX3CR1, and AIF1 were lower in autism tissue than in control tissue, with fold changes of 0.780 (P = 0.0056), 0.797 (P = 0.0083), 0.659 (P = 0.0029), and 0.808 (P = 0.0052), respectively." (PMID 24410870, 2014). "Population studies have revealed significantly reduced TREM2 protein levels in the postmortem brain tissues of patients with autism, with a negative correlation between TREM2 levels and autism severity scores." (PMID 41476737, 2025). "Nevertheless, given that there are some clinical reports indicating that the expression levels of microglia (TREM2, Cx3CR1) and astroglia markers (mainly GFAP) may contribute to autism pathology, suggest that astrocyte dysfunction may underlie the ASD phenotype observed here." (PMID 39024558, 2024). "Additionally, in patients with autism, there is a negative correlation between TREM2 protein levels and symptom severity, suggesting that TREM2 may play a protective role in neurodevelopmental disorders, such as autism." (PMID 40242752, 2025).
Autoimmunity (5 papers, 2018 to 2025). The occurrence of an immune reaction against the organism's own cells or tissues. "This indicates that the CD8+ T cell-related autoimmunity triggered by MI is enhanced after the deficiency of TREM2." (PMID 41041054, 2025). "Aside from ApoE and C1q/C3, iron inhibits α-secretase or ADAM-10, the enzyme involved in the generation of soluble TREM-2 (sTREM-2), linking again this biometal to autoimmunity." (PMID 30564191, 2018). "In addition to therapies promoting Trem2 and C1q, many clinical trials are investigating methods to increase systemic Tregs to treat autoimmune disorders and prevent rejection of transplanted organs." (PMID 37901247, 2023). "Indeed, TREM-2 blockade was demonstrated to exacerbate EAE and MS, linking this receptor to the CNS autoimmune disorders." (PMID 30564191, 2018). "Furthermore, the absence of TREM2 leads to an exacerbation of this autoimmunity." (PMID 41041054, 2025).
cerebrovascular diseases (5 papers, 2017 to 2025). "Interestingly, TREM2 has neuroprotective effects in cerebrovascular disease by suppressing TLR4 expression and the downstream NF-κB pathway and suppressing the expression of inflammation-induced cytokines." (PMID 41208869, 2025). "Therefore, Trem2 has become a new clinical therapeutic target for cerebrovascular diseases." (PMID 38348100, 2024).
experimental autoimmune encephalomyelitis (5 papers, 2014 to 2023). An autoimmune demyelinating disease of the central nervous system that is produced experimentally in animals by the injection of homogenized brain or spinal cord in Freund's adjuvant. "Intravenously administered TREM2-transduced myeloid precursor cells limit tissue destruction and facilitate repair by clearance of cellular debris during experimental autoimmune encephalomyelitis." (PMID 28592261, 2017). "However, research on an anti-mouse TREM2 antibody that competes for ligand binding and inhibits cell autonomous signaling revealed that TREM2 antagonism significantly worsened the outcome in experimental autoimmune encephalomyelitis (EAE)." (PMID 37396657, 2023). "It was reported that in cuprizone (CPZ) model of CNS demyelination, THY-Tau22 transgenic line, and experimental autoimmune encephalomyelitis (EAE), TREM2 was protective." (PMID 37013543, 2023).
Granuloma (5 papers, 2015 to 2023). A compact, organized collection of mature mononuclear phagocytes, which may be but is not necessarily accompanied by accessory features such as necrosis. "Trem2+ MΦs (cluster 9), which were recently identified as a distinct MΦ subset in human Mycobacterium leprae granulomas, are also present in our dataset." (PMID 36608122, 2023). "We also identify Trem2+ MΦs, which were recently identified as a MΦ subset in human M. leprae granulomas, as well as Nos2+ MΦs, a distinct MΦ phenotype in Mtb and S. enterica granulomas." (PMID 36608122, 2023). "TREM-2 signalling is required for the formation of giant cells and potentiation of macrophage fusion related to the formation of granulomas, a typical feature of the disease." (PMID 32508528, 2020). "Recent studies demonstrate the role of TREM receptors in the T cell immune response, the involvement of TREM-1 in the activation of systemic inflammation, and the role of TREM-2 in granuloma formation." (PMID 32508528, 2020). "Our findings showed that only triggering receptors expressed on myeloid cells 2–positive (TREM2-positive) macrophages (TREM2 macrophages) expressing angiotensin-converting enzyme (ACE) and lysozyme, diagnostic markers of sarcoidosis, were found to be increased in cutaneous sarcoidosis granulomas." (PMID 38038136, 2023). "We observed that the percentages of triggering receptor expressed on myeloid cells 2–positive (TREM2-positive) macrophages expressing angiotensin-converting enzyme (ACE) and lysozyme, diagnostic makers of sarcoidosis, were increased in cutaneous sarcoidosis granulomas." (PMID 38038136, 2023). "The DCs differentiation is potentiated also by activation of TREM-2/DAP12 pathway; moreover, this process is associated with the differentiation of macrophages to their fusogenic state and creation of large multinucleated giant cells typical for granulomas in sarcoidosis." (PMID 26166951, 2015). "Immunohistochemistry of sarcoidosis skin samples showed positivity for TREM2 and FBP1, which is consistent with the accumulation of CD68-positive cells in granuloma areas." (PMID 38038136, 2023).